VCAM1 (vascular cell adhesion molecule 1)
Diseases named in the same sentence as VCAM1 in open-access papers (continued):
Sharing a sentence is not in itself a finding about the gene and the disease.
melanoma (continued). "At the BBB, melanoma cells are able to convert hemodynamic signals into chemotactic responses and are arrested at sites of discontinuity in the tight junctions of the endothelial cells, where VCAM1, ICAM1, and E-selectin are expressed." (PMID 41463339, 2025). "Regarding modulations of MMPs and angiogenesis as the important molecular targets for the anti-metastatic action of apigenin, MMP2 in melanoma cells and MMP9 in melanoma and ovarian cancer cells, and vascular cell adhesion protein 1 (VCAM-1) in B16-BL6 melanoma cell were regulated." (PMID 38515580, 2024). "In vitro: the use of phenolic compounds, apigenin and/or quercetin, can inhibit the TNF-α-induced VCAM-1 expression and decrease the adhesion of melanoma cellsto lung sections.In vivo: inhibition of lung metastasis and the melanoma cell adhesion to vascular lung endothelium." (PMID 36986905, 2023). "However, here, we specifically wanted to distinguish between the VCAM-1-promoted intercalation of melanoma cells and a possible additional intercalation-promoting effect of the impaired barrier properties of pMBMECs." (PMID 37894438, 2023). "Extravasation of melanoma cells is promoted by adhesive interaction between the integrin very late antigen (VLA)-4 on melanoma cells and the immunoglobulin (Ig)-like cell adhesion molecule VCAM-1 on endothelial cells, as previously shown for the BBB and other types of endothelial layers." (PMID 37894438, 2023). "The binding of all three melanoma cell lines to vitronectin was comparable to VCAM-1." (PMID 37894438, 2023). "Several of the EMT-related genes with higher expression in NR patients encoded for molecules controlling adhesion (ITGB3, VCAM1, collagens, and others), interaction with extracellular matrix (VEGFA, MMP14, WNT5A, LAMA1, and others), and melanoma de-differentiation (KRT9, KRT10, EGFR, and others)." (PMID 37739939, 2023). "Inspired by these, we designed dual drug-loaded PLGA nanoparticles (Co-NPs) to co-deliver VCAM-1 inhibitor Suc and the chemotherapeutic doxorubicin (Dox) which could both effectively suppress primary melanoma and its lung metastases." (PMID 36839671, 2023). "VCAM-1 is an adhesion molecule that plays a major role in transendothelial migration of lymphocytes and cancer cells and, in agreement with this data, the pharmacological inhibition of FAK reduced VCAM-1 expression in tissues, in vivo, and impaired metastasis in a murine model of melanoma." (PMID 35216114, 2022). "We assessed ICAM-1 (CD54) and VCAM-1 (CD106) expression on melanoma cells by flow cytometry because they may influence responsiveness to 7HP349 therapy." (PMID 35552271, 2022). "Although here we have simulated channel-like environments in general, it remains possible that the introduction of channel coatings, such as VCAM-1 (which decorates micro-vessel walls), may also regulate the motile behavior of melanoma cells." (PMID 34493759, 2021). "Therefore, the bidirectional upregulation of VLA-4 on melanoma cells and VCAM-1 on fibroblasts via tumor MVs and hypoxia facilitates the adherence of cancer cells to stromal cells and consequently triggers melanoma progression." (PMID 34067929, 2021). "It has revealed that DABK-treated mice with melanoma had a lower number of tumor cells in their lungs, a lower expression of vascular cell adhesion molecule 1 (VCAM-1), and an enhanced CD8+ T-cell infiltration in the metastatic area when compared to those that did not get therapy." (PMID 34068618, 2021). "Similarly, the glycoprotein osteonectin interacts with VCAM‐1 and facilitates increased vascular permeability, resulting in enhanced melanoma cell extravasation." (PMID 33210465, 2020). "Under certain experimental conditions, melanoma cells may stimulate expression of VCAM-1 directly at pulmonary metastatic sites and VCAM-1 density has been found to modulate melanoma metastatic cell adhesion to the lung." (PMID 31591367, 2019).
melanoma (continued). "In addition, in those melanoma cells that do not express β3 integrins, β1 integrins instead play a role in promoting the transendothelial migration of melanoma cells by binding to vascular cell adhesion molecule 1 (VCAM-1) on ECs in the TME." (PMID 29703238, 2018). "Our previous study has shown that melanoma cell-secreted microvesicles can mediate the transformation of normal fibroblasts to CAFs and regulate the expression of vascular cell adhesion molecule-1, resulting in enhanced adhesion of melanoma cells and fibroblasts." (PMID 30285793, 2018). "However, similar to the B16.F10 melanoma model, there was a significant increase in endothelial expression of VCAM-1 for the group treated with anti-CD40 mAb in combination with sunitinib." (PMID 27385210, 2016). "In addition, we find that anti-CD40 antibodies and sunitinib therapy up-regulate ICAM-1 in B16.F10 melanoma and VCAM-1 in both models, thereby decreasing the endothelial barrier to lymphocyte recruitment." (PMID 27385210, 2016). "Turning on all three inputs, VCAM-1, IL-8, and IL-1β, represented the melanoma cell stimulus." (PMID 25225982, 2014). "In this study, we examined the roles of the melanoma cell inputs, IL-8, IL-1β, and VCAM-1 activation, and the endothelial cell outputs, actinomyosin contraction, junction disassembly, and actin remodeling, in melanoma-induced endothelial cell-cell junction breakdown." (PMID 25225982, 2014). "RNA interference silence of VCAM-1 inhibited melanoma migration and invasion." (PMID 23593320, 2013). "Moreover, establishment of pulmonary melanoma metastases was found to be followed by increases in VCAM-1 expression in organs frequently affected by melanoma metastases, including the brain." (PMID 23344048, 2013). "In addition, organ-specific increases in VCAM-1 expression correspond with reported clinical patterns of melanoma metastasis." (PMID 22481918, 2012). "Recently, VLA-4 mediated melanoma adhesion to VCAM-1 on activated endothelium was shown to support extravasation under the shear flow also in the absence of selectin ligands, indicating the potential of VLA-4 to serve as an adhesion molecule during metastatic spread of cancer." (PMID 22505933, 2012). "This was further confirmed by the enhanced adherence to VCAM-1 of PGE2-pretreated melanoma cells." (PMID 21867538, 2011). "This was further supported by in vitro experiments where RVL also inhibited IL-18 secretion, VCAM-1 expression and melanoma cell adhesion to tumor-activated HSE cells, three interrelated events regulating the microvascular arrest of circulating melanoma cells in the liver." (PMID 21569399, 2011). "Because IL-18 promotes the adhesion of B16 melanoma cells to the hepatic microvascular endothelium via VCAM-1-dependent mechanism, we next studied the effect of RVL on the VCAM-1 expression level in primary cultured hepatic endothelial cells given either recombinant murine IL-18 or B16M-CM." (PMID 21569399, 2011). "Moreover, this proadhesive activation was COX-2-dependent, which suggests for the first time that COX-2 is regulating murine and human melanoma cell adhesion to BMSCs via VLA-4/VCAM-1 mechanism." (PMID 21867538, 2011). "Similarly, the high-affinity interaction between integrin-α4 and VCAM-1 promoted trans-endothelial migration in melanoma cells." (PMID 19773759, 2009). "Indeed, the recent study on the effects of endostatin on experimental melanoma cells showed that VCAM-1 plays an important role in adhesion of these cells." (PMID 15700042, 2005). "Our single-cell RNA-seq data showed that zebularine treatment of melanoma cells significantly upregulated a panel of MHC-AgPPM genes, innate immune-associated genes (IFN-stimulated genes, chemokines, etc.), and genes involved in lymphocyte adhesion (such as Vcam1, Icam1, Icam2, and Sele)." (PMID 38755254, 2024).
melanoma (continued). "Moreover, treatment with B1R agonists could attenuate melanoma metastasis by inhibiting VCAM-1 expression, indicating the regulatory role of bradykinin and adhesion molecules in the host immune response of tumor cells." (PMID 37627528, 2023). "However, the intercalation of melanoma cells into the junction-compromised Il-1β-stimulated pMBMECs was stronger than the upregulation of VCAM-1 and thus may be a consequence of the weakened junctions of the pMBMECs." (PMID 37894438, 2023). "Similarly, a previous study showed that the C-terminal extracellular Ca2+ module of SPARC, a domain implicated in binding to endothelial cells 69 and to vascular cell adhesion molecule 1 (VCAM1) 70, is needed to enhance endothelial transmigration of melanoma cells via VCAM1 signaling." (PMID 33995652, 2021). "However, integrin ligands might also exert subtle inhibitory effects controlled by ligand density variation as has been exemplified by the inhibition of melanoma cell spreading induced by VCAM-1 presented at high densities." (PMID 31991896, 2020). "Also, of interest, the present DNA microarray data show that several groups of cell adhesion molecules (ICAM, integrin, VCAM-1, melanoma CAM, Cerebral endothelial CAM) that play an essential role in WBC migration from blood vessels to tissues are robustly regulated by VEGF agents." (PMID 19087268, 2008). "B16-BL6 melanoma cells exhibited robust VLA-4-dependent rolling and arrest on activated endothelial monolayers and on immobilized VCAM-1 under physiological shear stresses (0.7-2 dyn/cm2), independent of chemokine-related Gαi signaling." (PMID 42074287, 2026). "Melanoma typically invades nearby lymph nodes, where FAK signaling stimulates the expression of vascular cell adhesion molecule-1 (VCAM-1)." (PMID 39976799, 2025). "The FAK inhibitor PF-271 has been shown to significantly decrease VCAM-1 level, thereby reducing B16F10 melanoma cell adhesion and transmigration." (PMID 39976799, 2025). "In contrast to benign melanocytic lesions, malignant melanomas exhibit an elevated expression of VLA-4, enabling tumor cell migration through the vascular system into any tissue in which endothelial VCAM-1 is expressed." (PMID 39274345, 2024). "In this previous study, we showed that antibody blocking of VCAM-1 and VLA-4 significantly reduced the intercalation of melanoma cells into the pMBMECs." (PMID 37894438, 2023). "We then sought to portray the spatial relationship between inflamed huTECs as defined by their enhanced protein expression of VCAM1 or double‐positive VCAM1/STING and CD8+ T‐cells in melanoma samples." (PMID 38009521, 2023). "In good concordance with previous findings, we observed expression changes of several cellular adhesion molecules, cytokines, and chemokines, including VCAM-1, VEGF, CD105, or VCAM-1, in the HHSEC cells after interacting with melanoma cells." (PMID 37240247, 2023). "Among the markers associated with tumor aggressiveness, an increase in vascular cell adhesion molecule (VCAM)-1 levels has been identified in patients with concurrent OSA and melanoma, when compared with patients with melanoma alone." (PMID 36831404, 2023). "This analysis revealed 15 differentially expressed proteins (including CD31, VCAM-1, ANGPT2, CXCL8, and CCL20) in the hepatic endothelial cells after co-culture with melanoma cells." (PMID 37240247, 2023). "Specifically, VLA-4 has been shown to increase the adhesion of melanoma and sarcoma cells to cytokine-activated endothelium via INCAM-110/VCAM-1 interaction." (PMID 36497180, 2022). "Once secreted by melanoma cells, HMGB1 binds to RAGE, activating the endothelial cells with consequent increased expression of the adhesion molecules VCAM-1, ICAM-1, and E-selectin." (PMID 36012593, 2022). "Tinzaparin administration in mice injected with melanoma cells was capable of diminishing the metastatic potential to distant organs by disturbing the P-, L-selectin and VLA-4/VCAM-1 interconnections." (PMID 34208987, 2021).
melanoma (continued). "VCAM1, identified in 1989, was initially named INCAM-110 and later was termed VCAM1 because of its ability to mediate firm melanoma cell adhesion." (PMID 34281218, 2021). "Besides their immunological role in the metastatic progression of melanoma to the liver, inflammatory cytokines have also been implicated in the adhesion of circulating murine melanoma cells to the hepatic microvasculature through ICAM-1 and VCAM-1 adhesion molecules." (PMID 33138017, 2020). "Furthermore, in melanoma, α4 expressed on melanoma cells binds to its counter receptor VCAM-1 expressed on LECs with a high affinity and induces the adhesion of melanoma cells to LECs, indicating that α4 may participate in lymphangiogenesis and lymphatic metastasis in melanoma." (PMID 29703238, 2018). "This is in accordance with studies on colon carcinoma and melanoma, demonstrating significantly suppressed ICAM-1 and VCAM-1 expression, which have been shown to contribute to decreased leukocyte adhesion in vivo." (PMID 26943029, 2016). "Thus, melanoma-induced activation of VCAM-1 signaling may have similar effects." (PMID 25225982, 2014). "It has been shown that the interaction of melanoma cell integrin α4β1 (very late antigen-4, VLA-4) with VCAM-1 is critical for tumor cell arrest." (PMID 22481918, 2012). "In vitro, untreated and LPS-treated murine and human BMSC-conditioned medium (CM) increased VCAM-1-dependent BMSC adherence and proliferation of B16M and A375M cells, respectively, as compared to basal medium-treated melanoma cells." (PMID 21867538, 2011). "LPS did not significantly alter the expression of VLA-4 (very late antigen-4, counter receptor of VCAM-1) or LFA-1 (leukocyte functional antigen-1, counter receptor of ICAM-1) on melanoma cells either in vivo or in vitro." (PMID 16336680, 2005). "The arrest of B16F1 melanoma cells in the liver sinusoids (following mesenteric vein injection) induced focal expression of VCAM-1 and more diffuse expression of ICAM-1 around the melanoma cell arrest sites." (PMID 16336680, 2005). "Adhesion of ICAM1 and VCAM1 to melanoma cell integrins creates anchor points, and most intracranial melanomas use vascular co-optation rather than induce angiogenesis." (PMID 41463339, 2025). "Furthermore, oral administration of PF-271 has reduced cervical, inguinal, and popliteal VCAM-1 expression in C57BL/6 mice, supporting the potential use of FAK inhibitors in melanoma treatment." (PMID 39976799, 2025). "Additionally, Gal-9 disrupts the binding of CD44 to hyaluronic acid, Very Late Antigen-4 (VLA-4), and Vascular Cell Adhesion Molecule-1 (VCAM-1), interfering with key steps in melanoma cell metastasis." (PMID 40134029, 2025). "In particular, as compared to B16F1 melanoma, AT-3 tumors were enriched in mediators of leukocyte infiltration, including chemokines like RANTES, MCP-1 and − 5, fractalkine, CXCL9, 10 and 16, as well as endothelial adhesion molecules like ICAM-1 and VCAM-1." (PMID 38493157, 2024). "Furthermore, there is evidence that melanoma cells upregulate cell adhesion molecules such as VLA-4 that allows binding to the endothelial vascular cell adhesion molecule, VCAM-1, aiding melanoma extravasation." (PMID 37047054, 2023). "Additionally, we tested various surface molecules that have been previously suggested as potential candidates for eosinophil–melanoma cell interaction, such as CD11b, CD11a, CD18, CD54, CD49d and VCAM-1." (PMID 35565423, 2022). "Melanoma cells are able to secrete IL-1α and IL-1β, which in turn upregulate IL-6, IL-8, the intracellular adhesion molecule-1 (ICAM-1), and the vascular cell adhesion molecule-1 (VCAM-1) expression in endothelial cells." (PMID 35626056, 2022). "The melanoma cells lacking αVß3 integrins can make use of ß1 integrins instead to adhere to the endothelial ligand VCAM-1." (PMID 30657059, 2019).
melanoma (continued). "After establishing the disruptive effect of metastatic melanoma cells on endothelial monolayers and identifying IL-8 and VLA-4/VCAM-1 interactions as important triggers, we turned our attention to examining mechanistically how these tumor cell signals promote disruption of endothelial junctions." (PMID 28393886, 2017). "Furthermore, multiple cancer cell types including melanoma, sarcoma, renal, ovarian, and lymphoma are known to express VLA-4 on their surfaces which can mediate VCAM-1 signaling." (PMID 25225982, 2014). "Second, because IL-18 regulates melanoma metastasis occurrence via VLA-4-dependent B16M cell adhesion to HSE, the effects of RVL on IL-18 secretion and VCAM-1 expression by hepatic sinusoidal cells, and on the cancer cell response to IL-18 were studied in vitro." (PMID 21569399, 2011). "The expression of ICAM-1, VCAM-1, E-selectin and αv integrin was all induced to different degrees by the growth of melanoma tumors in the peritoneal cavity without liver metastasis in the mouse." (PMID 16336680, 2005). "LPS stimulation also increased the retention of B16F1 melanoma cells in the liver between 8–24 h, especially in the terminal portal venule region presumably through increased expression of adhesion molecules, ICAM-1 and VCAM-1." (PMID 16336680, 2005). "In a study on progression of mouse melanoma (B16-BL6) spontaneous metastasis, organ specific induction of VCAM-1 was observed in the cardiac, hepatic and cerebral vascular beds 4 weeks following the resection of primary tumors when metastatic pulmonary burden was maximal." (PMID 16336680, 2005). "ICAM1 inhibition, but not VCAM1 inhibition reduced melanoma cell retention." (PMID 39875968, 2025). "The binding of B16F-10 murine melanoma cells to mouse leptomeningeal cells could be blocked by VCAM-1 antibodies with no additive effect of blocking integrin β1 and β3." (PMID 37173970, 2023). "As shown for sialyl-Lewis(x/a)-negative melanoma cells, its function may be replaced by interactions of integrin α4β1 and endothelial vascular adhesion molecule (VCAM-1) mediating melanoma adhesion and subsequent extravasation under conditions of flow." (PMID 33172202, 2020). "With enhanced local expression of VCAM-1 and ICAM-1 around B16F1 cell arrest sites in the liver, LPS significantly increased the retention of melanoma cells in the liver, especially in the terminal portal venule regions between 8 and 24 h after intramesenteric injection of melanoma cells." (PMID 16336680, 2005). "Not surprisingly, LPS increased VCAM-1 expression and VEGF secretion by BMSCs from hematopoietic bones, which promoted melanoma cell adhesion to BMSCs via tumor COX-2-dependent VLA-4 activation." (PMID 21867538, 2011). "In the B16.F10 melanoma model, endothelial expression of ICAM-1 and VCAM-1 was not changed after treatment with agonistic CD40-antibody or sunitinib alone, but combining these treatments led to a synergistic increase in ICAM-1 (p=0.043) and VCAM-1 (p=0.017) surface expression." (PMID 27385210, 2016).